NPHP3-ACAD11 (NPHP3-ACAD11 readthrough (NMD candidate))
Gene: Protein-coding gene on chromosome 3 (132,558,142 to 132,722,459, reverse strand). Ensembl gene ENSG00000274810.
Genetic constraint (gnomAD): Loss-of-function variants: 13 observed, 22.59 expected, observed/expected ratio (o/e) 0.58, 90% interval 0.37 to 0.92. The upper end of that interval is the gene's LOEUF score, 0.92, which puts it in group 3 of 6, group 1 being the genes least tolerant of losing a copy. Missense variants: 188 observed, 236.25 expected, observed/expected ratio (o/e) 0.8, 90% interval 0.71 to 0.9. Synonymous variants: 84 observed, 86.02 expected, observed/expected ratio (o/e) 0.98, 90% interval 0.82 to 1.17.